RAC1 (Rac family small GTPase 1)
Diseases named in the same sentence as RAC1 in open-access papers (continued):
Sharing a sentence is not in itself a finding about the gene and the disease.
breast carcinoma (continued). "IR exposure of MCF-7 breast cancer cells was associated with a rapid activation of Rac1 and an induction of G2/M cell cycle arrest." (PMID 22494620, 2012). "Rac1, a Ras-like small GTPase, has been implicated in the control of cell growth and morphology and is believed to be associated with breast cancer progression." (PMID 22295219, 2011). "In summary, our data demonstrate that the CK1ε mutants found in breast cancer act as loss of function, suppress jWnt/β-catenin, and promote Wnt/Rac-1-mediated and NFAT-mediated pathways." (PMID 20507565, 2010). "Our data demonstrate that breast cancer-specific mutants of CK1ε act as loss of function in the Wnt/β-catenin pathway but activate the Wnt/Rac1/JNK and Wnt/Ca2+ pathways." (PMID 20507565, 2010). "Because Rac1 and Rac3 both have been implicated in breast cancer, we carried out a comparative study between the two isoforms." (PMID 16280046, 2005). "RAC1 mutations promote tumorigenesis in melanoma, non-small cell lung cancer, breast cancer, prostate cancer, colorectal cancer, head and neck cancer, testicular germ cell tumours, glioblastoma multiforme, hepatocellular carcinoma and thyroid carcinoma among others." (PMID 40396280, 2024). "To explore whether oncogenic alterations in Rho/Rac1/CDC42 signaling are further enriched in metastatic vs primary breast cancer, we compared the rate of missense mutations and copy number alterations (CNA) in 42 genes associated with these pathways." (PMID 37463901, 2023). "In addition, high expression of Rac1 was associated with poor disease-free survival (DFS) in the breast cancer patients." (PMID 32193458, 2020). "Moreover, overexpression of Rac1 has been shown to be associated with poor outcome in several human cancers, such as breast cancer, colorectal cancer, and leukemia." (PMID 32193458, 2020). "Consistently, we showed the prominent role of Rac1 in upregulating the R5P synthesis and nucleoside metabolism, thus promoting the repair of DNA damage caused by chemotherapy agents, and inducing chemoresistance of breast cancer cells to these drugs." (PMID 32193458, 2020). "We identified for the first time a putative NMU-mediated modulation of WNT-superfamily signaling associated with enhanced activation of the small GTPase RAC1 that may contribute to increased migration of NMUR2-positive SKBR3 breast cancer cells." (PMID 28423716, 2017). "As stimulation of ErbB3 by HRG causes a prominent activation of Rac1 in luminal breast cancer cells via P-Rex1, leading to a motile response, we investigated how silencing P-Rex1 could affect the regulation of gene expression by this growth factor." (PMID 27351228, 2016). "Given the relevance of the P-Rex1/Rac1 pathway in breast cancer progression, and since the Rac pathway controls a number of key functions implicated in gene expression, we decided to pursue an analysis of genes regulated by P-Rex1 in breast cancer cells." (PMID 27351228, 2016). "Consequently, loss of RhoGDIα caused increased Rho, Rac-1 and Cdc42 activities in breast cancer cells." (PMID 26554417, 2015). "The ELMO1, DOCK1, and RAC1 pathway has been implicated in: phagocytosis of Gram-negative bacteria by macrophages, T cell migration in primary lymphocytes, and actin cytoskeleton regulation during breast cancer metastasis." (PMID 25901943, 2015). "In summary, the results of the present study suggest that the cell junction of dormant MCF-7 breast cancer cells might be disrupted in association with the Rac1, which might be up-regulated upon ROCK inhibition." (PMID 24523903, 2014). "Moreover, a self-activating splice variant of RAC1, RAC1b, was shown to be overexpressed in breast cancer and lung cancer and is thought to mediate the epithelial–mesenchymal transition in lung epithelial cells." (PMID 24146998, 2013). "IR exposure of MCF-7 breast cancer cells was associated with a marked activation of Rac1 GTPase." (PMID 22494620, 2012).
breast carcinoma (continued). "The association of RCC2 and Rac1 with poor prognostic clinicopathological factors could help in the prediction of tumor progression, and thus targeted therapy could be helpful in the treatment of breast cancer." (PMID 39118792, 2024). "The association of RCC2 and Rac1 with poor prognostic parameters may serve as predictive indicators for aggressive tumors, thus implying that targeted therapy could be beneficial in the treatment of breast cancer." (PMID 39118792, 2024). "Further, recent studies have linked activating PI3Kα mutations to enhanced Rac1 and Yap signaling during breast cancer progression in vivo and suggest an invasive program that may be potentiated by mechanical alterations to the ECM that commonly occur during breast tumor progression." (PMID 32632100, 2020). "Finally, for breast cancer cells increased proliferation with increased substrate stiffness has been linked to increased invasiveness via various proliferative/invasive pathways, such as Rac1 and PI3K." (PMID 29136040, 2017). "This work identifies the P-Rex1/Rac1 axis as a potential therapeutic target for late recurring ER+ breast cancer." (PMID 42115169, 2026). "To validate the pivotal role of RAC1 in tumor development, we performed functional assays using five cell lines representing three cancer types: breast cancer (MDA-MB-231 and BT549), lung adenocarcinoma (A549 and NCI-H1395), and gastric cancer (AGS)." (PMID 39898257, 2025). "NaV1.5 can also mediate the activation of Rac1, which indicates the feasibility of inhibiting NaV1.5 for the treatment of breast cancer." (PMID 39673684, 2025). "Rac1 gene knockout increases chemotherapy sensitivity and reduces chemotherapy resistance in breast cancer." (PMID 39673684, 2025). "In summary, these observations provided persuasive evidence at the biological level to support the oncogenic role of RAC1 in breast cancer and lung adenocarcinoma." (PMID 39898257, 2025). "In this paper, the roles of NaV1.5 and Rac1 in EMT-mediated breast cancer progression were reviewed." (PMID 39673684, 2025). "HACE1 inhibits the progression of a variety of tumors, including breast cancer, lung cancer, prostate cancer, and osteosarcoma, by regulating the ubiquitination and proteasomal degradation of Rac1." (PMID 40948788, 2025). "Overall, the pharmacological and safety properties of the RAC1 inhibitor A41 open up prospects for clinical trials aimed at assessing the risks and benefits of targeting RAC1 in human cancer, particularly in breast cancer." (PMID 40633540, 2025). "The role of Rho GTPases, particularly Rac1, in cancer progression is increasingly recognized as a critical factor in driving breast cancer metastasis." (PMID 40629272, 2025). "Although the specific roles of NaV1.5 and Rac1 in breast cancer progression have been partially elucidated, the metastasis and drug resistance of breast cancer involve the interactions of multiple signaling pathways and genes." (PMID 39673684, 2025). "This study highlights the critical role of two VAV family members, VAV2 and VAV3, in regulating the mevalonate pathway in breast cancer cells through a RAC1‐ and SREBF‐dependent mechanism." (PMID 39119789, 2025). "High ITGB4 expression is a prognostic factor in CRC and is associated with drug resistance mechanisms in breast cancer, such as resistance to tamoxifen-induced apoptosis via the PI3K/Akt pathway and anoikis resistance through RAC1 signaling." (PMID 39401197, 2024). "HGF stimulates cell migration in breast cancer cells and oleocanthal attenuates this effect by suppressing the phosphorylation of Brk, paxillin, Rac1, and c-Met." (PMID 39203892, 2024). "In breast cancer, GAS7 was associated with CYFIP1 and WAVE2 complex to suppress breast cancer metastasis via blocking CYFIP1 and Rac1 protein interaction, actin polymerization, and β1-integrin/FAK/Src signaling." (PMID 38370374, 2024).
breast carcinoma (continued). "In breast cancer, RAC1 can also interact with oestrogen receptors α (ERα) that are predominantly found in the cell’s nucleus." (PMID 40396280, 2024). "p120 can facilitate the transformed growth of human breast cancer cells through Rac1 activation and Rac1-mediated MAPK signaling, and modulate the invasion and migration of GnRH-induced human ovarian cancer cells through modulating Rac1 and Cdc42." (PMID 39498333, 2024). "Previous studies have confirmed Rac1 expression in breast cancer and suggested its involvement in the cancer progression." (PMID 39118792, 2024). "It has been reported that p120 increases the migration and invasion ability of the epidermal growth factor receptor 2-induced breast cancer cells through inducing Rac1 and Cdc42 activity." (PMID 39498333, 2024). "MDA-MB-231 breast cancer cells were transfected with Rac1, Cdc42, or RhoA biosensors and treated with P18 at a concentration of 25 μg/mL for 3 h." (PMID 38927935, 2024). "These experiments suggest that DOCK4 and RAC1 promote the intercalation of breast cancer cells into the brain endothelium via regulating cell elongation but not filopodial protrusions in response to endothelial-derived growth factors, such as EGF." (PMID 38762624, 2024). "RAC1 overexpression was first identified to play a role in cancer progression in breast cancer, and investigations of RAC1 overexpression in other cancer types soon followed." (PMID 39001533, 2024). "In HER-2 breast cancer cells, Akt signaling stimulates Rac1 through Rac-GEF Tiam1, and PKC signaling reduces expression of a Rac1 inhibitor, RhoGD12." (PMID 38270460, 2024). "Upon EGF stimulation, RhoGDI1 phosphorylated at Ser174 binds to 14-3-3, promoting the dissociation of RhoA, Rac1 and Cdc42, which leads to their activation and results in cancer cell invasion and breast cancer metastasis." (PMID 39768163, 2024). "Apart from this, Rac1 has a role in diverse cellular processes, for example, membrane trafficking, hypoxia-stimulated breast cancer cell migration, cell adhesion, and cell proliferation." (PMID 38362155, 2024). "Inhibiting RAC1 with EHT1864 increased the effect of anti-breast cancer drugs in endocrine resistant breast cancer." (PMID 40396280, 2024). "Protein phosphatase 1B (PPM1B) dephosphorylates RhoGDI1 at Ser174, reduces RhoGDI1 interaction with 14-3-3, thereby inhibiting signaling of RhoA, Rac1, and Cdc42 in breast cancer cell migration." (PMID 39768163, 2024). "Activation of RAC1 can reduce the therapeutic response to trastuzumab in breast cancer and increase the resistance of TNBC cells to paclitaxel, but the specific mechanism of action is not completely clear." (PMID 37787041, 2023). "We found that the co-localization of POTEE with Rac1 is correlated with more aggressive breast cancer subtypes." (PMID 38098337, 2023). "Another study has shown that Rac1-modulated macropinocytosis is also required for the EGF-induced internalization of E-cadherin in breast carcinoma." (PMID 37132654, 2023). "LDHA can keep the small GTPase Rac1 in an active state, thereby promoting the growth of breast cancer cells in vitro and in vivo." (PMID 37190033, 2023). "It is well known that GPCR plays a related role through intracellular G protein, and it has reported that GPR116 receptor regulates RhoA and Rac1 to affect breast cancer metastasis through Gαq." (PMID 36895027, 2023). "Enhanced phosphorylation on Y14 of CAV1 increases focal adhesion turnover, activation of Rac-1, and migration/invasion in metastatic melanoma, as well as breast cancer cells." (PMID 38069269, 2023). "The improved EHop-016 derivative MBQ-167 demonstrated 10X higher efficacy at 100 nM IC50 for inhibition of Rac1 activation and 78 nM for Cdc42 activation in breast cancer cells." (PMID 37397366, 2023).
breast carcinoma (continued). "Label-free quantitative proteomic analysis of the proteome isolated from the MCF-7 breast cancer cell line, treated with 1 μM of doxorubicin, identified RAC1, CDC42, and RHOA GTPases that were inactivated by the ARHGAP1 protein." (PMID 37511111, 2023). "In breast cancer cells, persistent Rac1 activity enhanced escape of β4 integrin from lysosomal degradation depending on actin-related protein 2/3 and TBC1D2." (PMID 36639648, 2023). "Rac1 was reported to be overexpressed or hyperactivated in breast cancer, as well as in other various cancers, including prostate, testicular, ovarian, lung and gastric cancers." (PMID 37316799, 2023). "This parallel assessment allowed us to achieve close quantitative agreement of the modeled and observed dynamics of Cdc42 and Rac1 activity during cell ruffling in both breast cancer cells (MDA-MB-231) and MEF cell lines." (PMID 37371108, 2023). "It has been demonstrated that Rhein derivatives can strongly inhibiting breast cancer cell proliferation, migration, and invasion by inhibited Rac1 promoter activity and downregulated Rac1 protein expression." (PMID 36969843, 2023). "Pirin also interacts with breast cancer anti-estrogen resistance 1 (BCAR1) protein that activates RAC1." (PMID 38033031, 2023). "YAP1–TEAD4 has been implicated in TIAM1-mediated activation of Rho-family GTPase RAC1, and thus, promotes tumour metastasis in breast cancer cells." (PMID 37370765, 2023). "Most recently, it has been reported that LDHA can have an oncogenic effect in breast cancer cells by binding to the active, small GTPase Rac1, thereby inhibiting its interaction with its negative regulator and keeping Rac1 in its active state." (PMID 37190033, 2023). "Rac1, a small GTPase, is known to promote breast cancer lung metastasis and induce chemoresistance of breast cancer." (PMID 37550720, 2023). "It was previously shown that Rac1 is able to direct dynamic protrusion generation as well as ECM alignment in metastatic breast cancer cells." (PMID 35241781, 2022). "Upregulation of the Arp2/3 subunit, ARPC1B, is associated with very poor metastasis‐free survival of breast cancer patients, but inhibition of ARP2/3 prevents cycle progression through RAC1 transformation." (PMID 34967509, 2022). "CuB mediates the reorganization of cytoskeletal proteins in breast cancer cells via the Rac1/Cdc42/RhoA signaling pathway, which sheds new light on the suppression of breast cancer metastasis by CuB." (PMID 36362132, 2022). "The overexpression of Rac1 is associated with multi-drug resistance to the neoadjuvant chemotherapy, and targeting Rac1 is a potential strategy to overcome acquired chemoresistance in breast cancer." (PMID 36059952, 2022). "On the other hand, high levels of Rac1 activation have been found in cancers, such as the colon cancer cells and breast cancer cells 62,63, suggesting Rac1 activation contributes to tumorigenesis." (PMID 35154488, 2022). "We previously reported on the efficacy of MBQ-167, which blocks both Rac1 and Cdc42 in breast cancer cells and mouse models of metastasis." (PMID 36861094, 2022). "GPR116/ADGRF5 plays a critical role in promoting breast cancer progression and metastasis through the p63RhoGEF-RhoA/Rac1 signaling pathway." (PMID 36551877, 2022). "In invasive ductal carcinoma (IDC) patient tissues, high AQP5 expression did not correlate with Ras but positively correlated with Rac1, which makes Rac1 a candidate downstream target of AQP5 in breast cancer." (PMID 36212456, 2022). "DOCK4 activates Rac1 and promotes actin reorganization and formation of lamellipodia at the leading edge of breast cancer cells." (PMID 36059515, 2022). "GBP-2 inhibits breast cancer cell migration by inhibiting the activation of Rac1, while promoting the activation of CDC42 and RhoA." (PMID 35681772, 2022).
breast carcinoma (continued). "It was observed that protein interaction combinations of WASF3 with some members of WAVE complex and RAC1 are responsible for breast cancer aggressiveness and metastasis." (PMID 34967509, 2022). "Recently, we have studied the role of F-actin in the SNTA1 mediated signaling pathway in breast carcinoma cells and loss of SNTA1 tyrosine phosphorylation and decrease in Rac1 activation was observed in response to actin depolymerization." (PMID 35273919, 2022). "In summary, our study demonstrated that YAP1 can upregulate TIAM1 expression by binding to its enhancer, which subsequently activates RAC1 and induces invadopodia formation in breast cancer." (PMID 35773411, 2022). "In relevance to Nav1.5, the activation of Rac1 by Nav1.5 has been reported to stimulate the motile phenotype and migration of breast cancer cells." (PMID 35204811, 2022). "TCGA breast cancer samples showed a positive correlation of RAC1 with BRD4 and high expression of both proteins predicted poor prognosis and survival of breast cancer patients." (PMID 34803511, 2021). "Based on high expression of both RAC1 and BRD4 in human breast cancer samples, we investigated the effect of high and low expression levels of RAC1 and BRD4 on survival of breast cancer patients." (PMID 34803511, 2021). "Nonetheless, RAC1 activity appears to be critical to maintaining ER protein levels in ER+ breast cancer cells." (PMID 34373577, 2021). "Previous studies demonstrated that inhibiting the Rac1/Wave2/Arp2/3 signaling pathway in breast cancer cells and glioma cells resulted in the damage of cell adhesion." (PMID 34068233, 2021). "In contrast, lower expression of RAC1 was correlated with better survival of breast cancer patients." (PMID 34803511, 2021). "The status of Rac1-GTP was significantly related to increased mortality and risk of recurrence from breast cancer." (PMID 34221974, 2021). "We previously reported that the constitutive degradation of an endosomal small GTPase RhoB by the CUL3/KCTD10 E3 complex functions in EGF-induced Rac1 activation specifically in HER2-positive breast cancer cell lines, among other breast cancer subtypes." (PMID 34187934, 2021). "Overexpression of NCKAP1 also increased the invasion potential of breast cancer cells, in addition to the levels of Rac1 in the WASF3 immunocomplex, suggesting NCKAP1 acts to enhances Rac1 engagement." (PMID 33467681, 2021). "The aberrant EGFR activation controls cell migration, at least in part, through RAC1, which is overexpressed in human breast cancer cells." (PMID 33633298, 2021). "We identified a novel and potential therapeutic strategy by co-targeting BET bromodomain BRD4 and RAC1 signaling pathways in different molecular subtypes of breast cancer including luminal-A, TNBC and HER-2 positive breast cancer." (PMID 34803511, 2021). "In summary, our results showed a novel therapeutic strategy by co-targeting BET bromodomain BRD4 and RAC1 signaling pathways in different molecular subtypes of breast cancer including luminal-A, TNBC and HER-2 positive breast cancer." (PMID 34803511, 2021). "We have shown that loss of HACE1, an E3 ubiquitin ligase for RAC1, leads to enhanced RAC1 signaling that contributes to breast cancer development." (PMID 34373577, 2021). "HIF1α accumulation was also reduced in MCF7 breast cancer cells under hypoxia when RAC1 was knocked down." (PMID 33603169, 2021). "The analysis of our RNAseq data also showed an upregulation of the BCAR3 gene, engaged in enhanced cancer cell motility, by regulation of the balance between Rac1 and RhoA signaling in invasive breast cancer cells." (PMID 35008571, 2021). "Breast cancer has higher RAC1 expression than normal breast tissue, which can be activated through EGFR family members." (PMID 34373577, 2021). "Comparative study of pathway expression analysis in human and canine mammary tumors found upregulation of RAC1 gene expression and downregulation of MAPK signaling pathway in CMTs." (PMID 34679042, 2021).